PANK2 (pantothenate kinase 2)
Diseases named in the same sentence as PANK2 in open-access papers (continued):
Sharing a sentence is not in itself a finding about the gene and the disease.
neuroblastoma (5 papers, 2012 to 2021). Neuroblastoma (NB) is the most common solid, extracranial childhood tumor. "The same authors found a reduced capacity to develop neurites in neuroblastoma cells silenced for PANK2." (PMID 34439650, 2021). "It was shown to increase total CoA concentration and tubulin acetylation in neuroblastoma cells silenced for PANK2 and to permeate the blood brain barrier in orally dosed monkeys." (PMID 34439650, 2021). "Fosmetpantotenate restored coenzyme A in short-hairpin RNA pantothenate kinase 2 gene-silenced neuroblastoma cells and was permeable in a blood-brain barrier model." (PMID 29522513, 2018). "In shRNA PANK2-knockdown neuroblastoma cells, fosmetpantotenate increased CoA and tubulin acetylation levels." (PMID 29522513, 2018). "In contrast, fosmetpantotenate has been shown to significantly increase intracellular CoA levels and increase tubulin acetylation in vitro in neuroblastoma cells that have been silenced for PanK2 expression, presumably via access to mitochondrial PanK2." (PMID 28567317, 2017). "Therefore, we generated HEK293T (human embryonal kidney) and SH‐SY5Y (human neuroblastoma) cells in which PANK2 protein levels were downregulated." (PMID 31701655, 2019).
thyroid cancer (5 papers, 2019 to 2022). "PANK2 has been reported to be a potential therapeutic target in thyroid cancer." (PMID 34722508, 2021). "This method was validated by stably transfecting two standard human thyroid cancer cell lines (BCPAP and 8505C) with four distinct genes (DDX19B, NEMP1, PANK2, UBALD1) and profiling their transcriptome before and after the transfection." (PMID 33302383, 2020). "Expression data for the GMR Theory validation on thyroid cancer cell lines BCPAP and 8505C were collected from GSE97031 (transfection with NEMP1), GSE97028 (DDX19B), GSE97030 (PANK2) and GSE97427 (UBALD1)." (PMID 31349573, 2019). "Nonetheless, we validated the relationship between the GCH score and the transcriptomic consequences of manipulating the gene expression by stably transfecting DDX19B, NEMP1, PANK2, and UBALD1 on the papillary (BCPAP) and anaplastic (850C) human thyroid cancer cell lines." (PMID 34209090, 2021).
Azoospermia (4 papers, 2012 to 2023). Absence of any measurable level of sperm,whereby spermatozoa cannot be observed even after centrifugation of the semen pellet. "The Pank2 adult knockout mice did not exhibit gross defects in anatomy or behavior, with the exception of azoospermia for Pank2 knockout mice." (PMID 22815849, 2012).
HARP syndrome (4 papers, 2016 to 2019). "In addition, UDP_4964 was diagnosed with HARP syndrome (OMIM:607236) due to compound heterozygous PANK2 mutations, with PANK2 ranking first of 221 genes." (PMID 26562225, 2016).
retinal degeneration (4 papers, 2012 to 2025). Degeneration of the retina. "The knockout murine model of the orthologous Pank2 gene is known to manifest retinal degeneration through electroretinography, pupillary response and histology analyses." (PMID 40554626, 2025). "A PanK2-knock-out (KO) mouse was developed in 2005, yet it recapitulated only few features of the disease like retinal degeneration and impaired mitochondrial function." (PMID 24058333, 2013). "We were unable to confirm histological evidence of retinal degeneration or significant body weight reduction in the Pank2 knockout animals up to age 6 months compared to littermate controls, in contrast with the previous report." (PMID 22815849, 2012).
chorea-acanthocytosis (2 papers, 2013 to 2021). Chorea-acanthocytosis (ChAc) is a form of neuroacanthocytosis and is characterized clinically by a Huntington disease-like phenotype with progressive neurological symptoms including movement disorders, psychiatric manifestations and cognitive disturbances. "Since this enzyme is localized in mitochondria, the similar pathological manifestations of PKAN and chorea-acanthocytosis may be related to the importance of both PANK2 and VPS13A in aspects mitochondrial physiology dependent on normal lipid homeostasis." (PMID 34216812, 2021). "Chorea-acanthocytosis (ChAc) relates to mutations in VPS13A, McLeod Syndrome (MLS) has mutations in XK, Huntington’s Disease-like 2 (HDL2) in JPH3, and panthotenate kinase-associated neurodegeneration (PKAN) in PANK2." (PMID 24098554, 2013).
dementia with Lewy bodies (2 papers, 2009 to 2017). "Less commonly, PAGF is caused by Lewy body disease, pantothenate kinase 2 gene mutation, pallidonigroluysian atrophy (PNLA), and primary lymphoma primarily affecting the basal ganglia." (PMID 29051824, 2017). "Furthermore, accumulation of aggregated, insoluble aSyn is a hallmark of many other neurodegenerative diseases, including sporadic PD, dementia with Lewy bodies (DLB), multiple system atrophy (MSA), the Lewy body variant of Alzheimer's disease, and PANK2-linked neurodegeneration." (PMID 19203374, 2009).
focal dystonia (2 papers, 2022 to 2025). A dystonia that is localized to a specific part of the body. "This included hypomyelinating leukodystrophy-14, NBIA/PKAN, CASK-related disorders, presumed PANK2 mutations (6 cases), and other idiopathic focal dystonia that spread out to paraspinal muscles (1 case)." (PMID 40864051, 2025). "The pathogenicity of this variant is well-documented in three Chinese patients with focal dystonia, radiological signs of NBIA and compound heterozygous PANK2 mutations." (PMID 35180557, 2022).
Glutaric acidemia type 1 (2 papers, 2023 to 2025). "The genetic dystonias were associated with the following genes: TOR1A, THAP1, SGCE, KMT2B, HPRT1 (Lesch Nyhan disease), PANK2 and GCDH (Glutaric Aciduria type 1)." (PMID 36445406, 2023).
iron deficiency (2 papers, 2024 to 2025). "In additional works, PANK2 silencing by siRNA in several human cell lines leads to a reduced proliferation rate, accompanied by a paradoxical iron deficiency and increased TfR1 expression levels." (PMID 40003902, 2025).
malaria (2 papers, 2016). Malaria is a serious and sometimes fatal disease caused by a parasite that commonly infects a certain type of mosquito which feeds on humans. "Although two eukaryotic-type putative pantothenate kinase genes (PanK1 and PanK2) have been identified in all malaria parasite species, their role in the development of Plasmodium life cycle stages remains unknown." (PMID 27644319, 2016).
neuroferritinopathy (2 papers, 2011 to 2022). Neuroferritinopathy is a late-onset type of neurodegeneration with brain iron accumulation (NBIA) characterized by progressive chorea or dystonia and subtle cognitive deficits. "One of the PANK2-negative eye-of-the-tiger sign case was multiple system atrophy and two were neuroferritinopathy." (PMID 22398981, 2011).
Childhood onset (1 paper, 2012). Onset of disease at the age of between 1 and 5 years. "PKAN is a childhood-onset extrapyramidal disorder with aberrant iron metabolism caused by a mutation of the pantothenate kinase-2 (PANK2) gene." (PMID 21808735, 2012).
colon carcinoma (1 paper, 2013). "It has been reported that the loss of one subset of kinases including PANK2 resulted in reduced β-cat–dependent transcription in colon carcinoma cells, representing potential targetable therapeutic genes." (PMID 23658834, 2013).
diabetes (1 paper, 2017). "Mutations of the PanK1 and PanK2 genes are associated with PanK-dependent neurodegeneration (PKAN) and diabetes." (PMID 28832533, 2017).
epilepsy (1 paper, 2026). A brain disorder characterized by episodes of abnormally increased neuronal discharge resulting in transient episodes of sensory or motor neurological dysfunction, or psychic dysfunction. "We demonstrated that HAGH, OSBPL1A, and PANK2 constitute core pathogenic mechanisms in epilepsy." (PMID 41810643, 2026).
Hyperglycemia (1 paper, 2023). An increased concentration of glucose in the blood. "It has been described in numerous cases of non-ketotic hyperglycemia, Wilson disease and infrequently in some patients with Pantothenate kinase 2 deficiency." (PMID 37810989, 2023).
kernicterus (1 paper, 2023). A term used pathologically to describe BILIRUBIN staining of the BASAL GANGLIA; BRAIN STEM; and CEREBELLUM and clinically to describe a syndrome associated with HYPERBILIRUBINEMIA. "In contrast, CP-Kernicterus and CP-Preterm groups showed normal putaminal glucose metabolism associated with pallidal glucose hypometabolism, whilst the PANK2 group showed apparently normal putaminal and pallidal glucose metabolism." (PMID 36445406, 2023). "Putaminal hypometabolism occurred in 7/10 aetiological categories, except PANK2, CP-Kernicterus and CP-Pre-term cases." (PMID 36445406, 2023). "Cerebellar hypometabolism occurred in HPRT1, PANK2, CP-Kernicterus and CP-Preterm." (PMID 36445406, 2023). "Insula hypometabolism was observed in HPRT1, PANK2, CP-Kernicterus and CP-Preterm." (PMID 36445406, 2023). "HPRT1, PANK2, CP-Kernicterus and CP-Preterm all exhibited insula glucose hypometabolism." (PMID 36445406, 2023). "It is also notable that three other distinct aetiological groups apart from PANK2 exhibit awake resting FDG-PET cerebellar glucose hypometabolism, namely HPRT1, CP-Kernicterus and CP-Preterm." (PMID 36445406, 2023).
neuropathy (1 paper, 2019). A disorder affecting the nervous system that manifests with pain, tingling, numbness, and/or muscle weakness. "It has also been reported that two patients with pantothenate kinase-associated neuropathy and PANK2 mutations have high QSM values in the GP and SN." (PMID 31501698, 2019).
parasitemia (1 paper, 2016). "RT-PCR analysis with similar amounts of RNA (60 ng) isolated from the same amount of blood extracted from similar infected blood parasitemia (~1%) confirmed that the transcription levels of PanK1 and PanK2 and other unrelated genes are similar in Pyp230p(−) parasites compared to WT parasites." (PMID 27644319, 2016).
schizophrenia (1 paper, 2021). A major psychotic disorder characterized by abnormalities in the perception or expression of reality. "This locus harbors four strong candidate genes for schizophrenia: attractin (ATRN), pantothenate kinase 2 (PANK2), oxytocin (OXT), and arginine–vasopressin (AVP)." (PMID 34869343, 2021).
synucleinopathy (1 paper, 2013). A neurodegenerative disease that is characterized by the abnormal accumulation of aggregates of alpha-synuclein protein in neurons, nerve fibers or glial cells. "As a result HSS was consistently considered a form of synucleinopathy with potential implications for PANK2-related cellular pathways on the pathogenesis of other Lewy body disorders, including Parkinson's disease." (PMID 22416811, 2013).
neurodegenerative disease (29 papers, 2010 to 2025). A disorder of the central nervous system characterized by gradual and progressive loss of neural tissue and neurologic function. "Disruption of the mitochondrially localized PanK2 isoform in humans results in the neurodegenerative disease Pantothenate Kinase-Associated Neurodegeneration (PKAN)." (PMID 37762222, 2023). "PKAN is a relentlessly progressive neurodegenerative disease caused by mutations in the PANK2 gene that result in insufficient CoA production." (PMID 35204826, 2022). "Pantothenate kinase 2‐associated neurodegeneration (PKAN) is a rare neurodegenerative disease caused by mutations in the pantothenate kinase 2 (PANK2) gene." (PMID 32705819, 2020). "Pathogenic variants in PANK2 and COASY lead to two early‐onset neurodegenerative diseases: pantothenate kinase‐associated neurodegeneration (PKAN) and CoA synthase protein‐associated neurodegeneration (CoPAN)." (PMID 31701655, 2019). "But we can look at research on PANK2-linked neurodegenerative diseases for clues." (PMID 40446021, 2025). "PKAN is a severe neurodegenerative disease caused by mutations in the human pantothenate kinase 2 (PANK2)-encoding gene and the molecular basis of this devastating disease are largely unknown." (PMID 22912811, 2012). "In addition, human PanK2 is highly expressed in the brain and mutations in the human PANK2 gene result in a progressive neurodegenerative disease, called PKAN (Pantothenate Kinase Associated Neurodegeneration)." (PMID 23152917, 2012). "Mutations in CoA synthesis enzymes PANK2 and COASY cause the neurodegenerative diseases pantothenate kinase associated neurodegeneration (PKAN; MIM #234200) and COASY protein associated neurodegeneration (CoPAN; MIM #615643) respectively." (PMID 41279021, 2025).
movement disorder (10 papers, 2012 to 2025). Neurological conditions resulting in abnormal voluntary or involuntary movement, which may impact the speed, fluency, quality and ease of movement. "In summary, we propose that loss of pantothenate kinase 2 disrupts dopamine homeostasis, causing the movement disorder observed in humans." (PMID 31660701, 2019). "The discovery of the first genetic determinant for a subtype of these movement disorders, namely variants in the pantothenate kinase 2 (PANK2) gene, together with the increased access to deep sequencing technologies, paved the way for the search and identification of several genetic associations." (PMID 40867110, 2025). "In contrast, both Pank2 mutant and wild type mice fed pantothenate (vitamin B5) deficient diets resulted in a progressive movement disorder in wild type mice and an early death in PANK2 mutant mice indicating the importance of pantothenate metabolism in PKAN." (PMID 23634310, 2013). "Comparative Genomic Hybridization (CGH)-array and gene testing for mutations in PLA2G6, PANK2 and SPG7 were negative, as well as NGS-based panel screening of 102 genes associated with movement disorders in childhood." (PMID 39063023, 2024). "A Pank2 knockout mouse was generated using gene disruption, but did not exhibit any behavioral or movement disorder, and did not accumulate iron in the brain, unlike the human PKAN disease." (PMID 22815849, 2012). "Evaluation of the Pank2(−/−) adult mice did not reveal a movement disorder, and histological analyses of brain sections were unremarkable." (PMID 22815849, 2012).
neurological disorder (4 papers, 2017 to 2022). "PANK-associated neurodegeneration (PKAN), formerly known as Hallervorden–Spatz disease, is a rare, life-threatening neurologic disorder that affects the CNS and arises from mutations in the human PANK2 gene." (PMID 35197056, 2022). "PKAN is a life-threatening neurological disorder that can be caused by a variety of PANK2 mutations that affect protein expression, enzyme activity and/or stability, resulting in loss or reduction of kinase activity." (PMID 35197056, 2022). "Mutations in the PANK2 gene lead to the development of PKAN, a severe and often devastating neurological disorder characterized by the sign of focal iron accumulation in the brain." (PMID 36361705, 2022).
retinopathy (4 papers, 2013 to 2025). "A mouse with PANK2 knockout also exhibited progressive photoreceptor degeneration, providing a PKAN retinopathy model." (PMID 30360383, 2018). "This Pank2-/- mouse model recapitulates some aspects of human PKAN retinopathy and can therefore serve as a useful model for assessing PKAN retinopathy therapeutics." (PMID 40554626, 2025).
tumor (4 papers, 2015 to 2025). "We also validated TTC1, PANK2 and G6PD expression levels in tumor by RT-qPCR." (PMID 41268553, 2025). "Analyzing the whole-blood expression signature of four growth factor-related genes (ARAF, BRAF, KRAS, and RAF-1) and four genes involved in metabolism (ATP6V1H, OAZ2, PANK2, and PLD3), combined with tumor grade, they were able to predict the efficacy of PRRT with an accuracy of 95%." (PMID 33809226, 2021).
cancer (3 papers, 2009 to 2022). A tumor composed of atypical neoplastic, often pleomorphic cells that invade other tissues. "Several other interesting candidate genes were also identified such as CAMK1, STK6, PANK2 and EPHB1, all of which have been previously reported as being involved in cancer." (PMID 19519883, 2009). "Additionally, we also independently generated PANK1, PANK2, or PANK3 knockout clones in multiple different cancer cell lines to validate the band specificity and serve as a negative control for the antibodies." (PMID 36139163, 2022). "Although DDX19B and PANK2 (but not NEMP1 and UBALD1) were synergistically expressed with SPINT2 in PTC, there are no reports relating these genes with SPINT2 in any form of cancer." (PMID 32887258, 2020).
infection (1 paper, 2009). The state of being infected such as from the introduction of a foreign agent such as serum, vaccine, antigenic substance or organism. "In terms of common metabolic genes, pantothenate kinase 2 (PANK2), the first enzyme in the biosynthetic pathway for coenzyme A production, was upregulated in these diverse cell types in response to T. cruzi-infection." (PMID 19480704, 2009).
PANK2 also shares sentences with these, for which no sentence is quoted: aceruloplasminemia (5 papers); genetic disorder (4); Alzheimer disease (3); Ataxia (2); dementia (2); Friedreich ataxia (2); infantile neuroaxonal dystrophy (2); retinitis pigmentosa (2); attention deficit-hyperactivity disorder (1); autism (1); autism spectrum disorder (1); autosomal recessive disease (1); central nervous system disease (1); Cognitive impairment (1); corneal dystrophy (1); developmental delay (1); epileptic encephalopathies (1); fatty acid oxidation (1); frontotemporal dementia (1); glioma (1); Hydrocephalus (1); hypomyelinating leukodystrophy-14 (1); iron overload (1); language disorder (1); Lesch Nyhan disease (1); Leukoencephalopathy (1); McLeod Syndrome (1); multiple sclerosis (1); multiple system atrophy (1); neurodevelopmental disorder (1).
A further 8 diseases each share a sentence with PANK2 in 1 paper.